PIK3CA (phosphatidylinositol-4,5-bisphosphate 3-kinase catalytic subunit alpha)
Diseases named in the same sentence as PIK3CA in open-access papers (continued):
Sharing a sentence is not in itself a finding about the gene and the disease.
breast cancer (continued). "PIK3CA is probably the most commonly mutated gene found in human breast cancers and is also mutated in many other solid cancer types." (PMID 29523855, 2018). "We also tested for the most common PIK3CA mutations, as PIK3CA mutations have been reported to be an early event in ER + breast cancer and are found in more than 30% of ER + primary treatment naive breast cancers." (PMID 30083595, 2018). "Here, we showed that the levels of ERα phospho-Ser167 were significantly higher in postmenopausal ER-positive, HER2-negative breast cancers that harbored PIK3CA mutations when compare to their wild-type counterparts." (PMID 29707142, 2018). "Considering the actionability of specific alterations based on OncoKB, CDKN2A homozygous deletion (level 4 evidence), and both oncogenic mutations in PIK3CA were considered clinically actionable (level 3A evidence for breast cancer)." (PMID 29755676, 2018). "One of the alternated key cancer pathway components of luminal breast cancers are PIK3CA mutations occurring in approximately 40% of patients." (PMID 30595753, 2018). "The clinical significance of PIK3CA mutations in breast cancer remains complicated and controversial in literatures." (PMID 29636477, 2018). "For example, the highly significant mutations in genes like PIK3CA or KRAS are observed in ~30% of breast cancer patients." (PMID 30374409, 2018). "PIK3CA mutations are also frequently mutated in HR positive breast cancer and are frequently associated with the luminal B subtype of breast cancer." (PMID 30148117, 2018). "In preclinical studies, pictilisib had antitumor activity in breast cancer models harboring PIK3CA mutations and/or amplification of HER2, although several models without these mutations were also sensitive to pictilisib treatment." (PMID 30185228, 2018). "The Cancer Genome Atlas Network reported that PIK3CA is the most frequent mutated gene in the luminal A (49%) and luminal B (32%) breast cancer subtypes." (PMID 29707142, 2018). "Most of the somatic mutations identified were private to one of the metastatic deposits and the likely pathogenic hotspot PIK3CA K111T mutation, a recurrently mutated residue in breast cancer, was private to and clonal in the brain metastasis #2 (BM2)." (PMID 29755676, 2018). "There has been controversy regarding the utility of PIK3CA mutations as a biomarker for HER2-positive breast cancer." (PMID 29700710, 2018). "All except one of the cases positive for a PIK3CA mutation at baseline had the same mutation detectable at the end of treatment (1/37 undetectable, 2.7%), consistent with the probable truncal nature of PIK3CA mutations in breast cancer." (PMID 29497091, 2018). "Although PIK3CA mutations (and especially c.3140A > G) are common in breast cancer, the genetic profile strongly suggested that the lung tumours were metastases from the tumour in the breast." (PMID 28347348, 2017). "In genome-doubled breast cancers, the majority of PIK3CA mutations were found to precede the genome duplication event, with a frequency significantly higher than would be expected by chance (P < 0.0001)." (PMID 29170395, 2017). "Hyperactivation of the PI3K pathway occurs in 70% of breast cancers; and approximately 30% of breast cancers have mutations in PIK3CA." (PMID 28061482, 2017). "For example, more than 46.6% of luminal-A breast cancer samples have PIK3CA mutated, whereas only 35.5% of all breast cancer samples contain PIK3CA mutations." (PMID 28392480, 2017). "Pik3ca mutations, which are very frequent in human breast cancer, are found spontaneously in two of the models (6DT1 and MVT1), and as a transgene in one model (HRM1)." (PMID 28430642, 2017). "The tree shrew breast cancer model best demonstrated a subset of human breast cancer with the PTEN/PIK3CA mutations." (PMID 28585435, 2017).
breast cancer (continued). "Mutations in the PIK3CA gene were recently associated with reduced response of breast cancer patients to trastuzumab and/or lapatinib neoadjuvant therapy." (PMID 27933395, 2017). "Aberrant expression of the PI3K/AKT/mTOR pathway is a frequent phenomenon in breast cancer and it is the result of a PIK3CA mutation, which corresponds to the PI3K p110 catalytic subunit, and more specifically to isoform α." (PMID 29064423, 2017). "Although heterogeneity in the PIK3CA mutation status between primary tumors and corresponding lymph nodes or distant organ metastases is reportedly rare for colorectal and breast cancers, limited information is available with regard to ESCC." (PMID 28068934, 2017). "The significant enrichment for clonal mutations and the significant tendency for mutations in PIK3CA to precede genome doubling remained significant when focusing on ER-positive breast cancers or luminal breast cancers." (PMID 29170395, 2017). "While it has been previously shown that H1047R has a superior oncogenic potential than E545K in transgenic mammary cancer models, the potential of different PIK3CA mutations in conferring resistance to upstream inhibition has not been previously explored." (PMID 28532501, 2017). "In summary, these results collectively demonstrate that therapeutic targeting of Rac is a promising therapeutic strategy for breast cancer, particularly in cancers harboring activating mutations in PIK3CA or amplification of HER2." (PMID 28423521, 2017). "The PI3K/AKT signaling pathway is frequently activated in more than 50% of human breast cancers and most commonly through mutational activation of the PIK3CA gene." (PMID 28388580, 2017). "Our study further argues that PIK3CA amplification or PIK3CA overexpression is more relevant than PIK3CA mutation status in breast cancer." (PMID 28387221, 2017). "Of the 776 breast cancer tumor samples with clinical data available, 358 were luminal subtype and 137 harbored the PIK3CA mutation." (PMID 28392480, 2017). "Some recent studies reported improved clinical outcome in patients with luminal breast cancer harboring PIK3CA activating mutations." (PMID 28858218, 2017). "Regarding trastuzumab therapy, activating mutations in the PIK3CA gene have been described to be associated with a poorer therapy outcome in breast cancer patients." (PMID 27933395, 2017). "Two cases with PIK3CA mutated breast cancer had partial responses to a combination of PIK3CA inhibitor, CDK4/6 inhibitor and hormonal therapy." (PMID 28915716, 2017). "Recent studies have shown how PIK3CA mutations interact with other mutations in a breast cancer survival network." (PMID 29262614, 2017). "Accumulating evidence suggests that mutation of PIK3CA is an early event in breast cancer and is more likely to play a role in breast tumor initiation than in invasive progression." (PMID 29179495, 2017). "Low p-Akt levels have previously been observed in breast cancer cell lines with PIK3CA mutations, demonstrating possible Akt-independent effects of some mutations in PIK3CA." (PMID 28002804, 2017). "The activating mutation of PIK3CA is frequently observed in breast cancers, particularly luminal-type cancer, which leads to hyperactivation of the AKT signaling pathway." (PMID 29108265, 2017). "Somatic mutations in PIK3CA are frequently found in a number of human cancers, including breast cancer, altering cellular physiology and tumour sensitivity to chemotherapy." (PMID 28393905, 2017).
breast cancer (continued). "For instance, PIK3CA mutation associates good prognosis in breast cancer patients, and PIK3CA amplification predicts increased survival in colorectal cancer." (PMID 28060766, 2017). "Mutations of the PIK3CA gene are described in 25%–40% of breast cancers and in 30% of colorectal cancer, while PIK3CA mutations in endometrial cancer are often coincident with PTEN inactivation." (PMID 28353628, 2017). "We demonstrate that, among breast cancer cells, mutations in PIK3CA and/or HER2 are predictive of increased sensitivity to Rac inhibition with EHT1864." (PMID 28423521, 2017). "Although no clinical evidence is currently available in terms of their actionability in PTs or sarcomas, clinical data support the potential targeting of these AKT, ERBB2, and PIK3CA hotspot mutations in breast cancer (OncoKB level of evidence 3A)." (PMID 29043292, 2017). "Mutations in PIK3CA occur in approximately one-third of breast cancers, and these mutations have been implicated in the development of trastuzumab resistance." (PMID 28750640, 2017). "One of the genes that is often mutated and over-active in breast cancer encodes an enzyme called PIK3CA." (PMID 28561737, 2017). "Consistently, T47D breast cancer cells with the H1047R mutation in PIK3CA were sensitive to the p110α inhibitor BYL719 measured by cell viability assay, but exhibited a lower response when PTEN was knocked down." (PMID 28002804, 2017). "In 8 breast cancer patients with stage IV disease in which PIK3CA somatic mutation was identified in both FFPE and plasma samples, mutant cfDNA and tumor markers CA15-3 and CEA were quantified in a total of 27 serial plasma samples." (PMID 28330468, 2017). "Recently, results were published suggesting that activating PIK3CA mutations are associated with reduced efficacy of trastuzumab- and lapatinib-based therapies in breast cancer patients." (PMID 27933395, 2017). "In this study, we compare the clinical information provided by PIK3CA mutation quantification using array-based dPCR, in plasma samples from ER positive breast cancer patients, with tumor markers 15-3 and CEA and computed tomography (CT) scan assessments." (PMID 28330468, 2017). "In breast cancer, the PIK3CA-mutated signalling pathway and 26 S proteasome genes were proved to be associated with patients’ prognosis by gene microarrays and signalling network analysis." (PMID 29123252, 2017). "As expected, administering these drugs together with the PIK3CA inhibitor caused breast cancer cells to die." (PMID 28561737, 2017). "Heterozygous knock-in c.3140A>G and c.1633G>A mutations in the PIK3CA gene were found to activate multiple oncogenic pathways and promote cell growth and invasion in vitro for human breast cancer and colon cancer cell lines." (PMID 29152088, 2017). "PIK3CA mutation frequencies are different among breast cancer subtypes: 34.5–45%, 22.7–39% and 8.3–25% in HR+, HER2+ and in triple negative breast cancers (TNBC), respectively." (PMID 29100327, 2017). "The PIK3CA gene mutation is the most frequently observed in this pathway, in particular in luminal breast cancers." (PMID 28241486, 2017).
breast cancer (continued). "The Cancer Genome Atlas (TCGA) breast cancer analysis found PIK3CA mutation rates of 45% in luminal A, 29% in luminal B, 39% in HER2+, and 9% in the basal-like subtypes, respectively." (PMID 29100327, 2017). "Four breast cancer patients had their PIK3CA mutation status determined, with one receiving BLY719 (PI3K inhibitor) in a clinical trial as a result, while a patient with a wild-type RAS mucinous ovarian carcinoma received cetuximab." (PMID 28196074, 2017). "Whereas PIK3CA mutations appear to occur late in the development of many cancers, we found PIK3CA mutation to be an early, clonal event in breast cancer." (PMID 29170395, 2017). "In contrast, entities such as breast cancer or HNC display a predominance of PIK3CA mutations (around 40%, for an overall mutation rate of KRAS, NRAS and HRAS inferior to 5% in both cases)." (PMID 28532501, 2017). "The PIK3CA gene has also been found to be oncogenic and is well implicated in many cancers, like cervical cancer, breast cancer." (PMID 28900470, 2017). "By contrast, only a minimal association was suggested between PIK3CA and clinical outcome in a retrospective analysis of breast-cancer samples from the BOLERO2 clinical trial." (PMID 29137436, 2017). "To understand the function of PIK3CA mutations in luminal A breast cancer, we applied our recently-proposed Cancer Hallmark Network Framework to investigate the network motifs in the PIK3CA-mutated luminal A tumors." (PMID 28392480, 2017). "Among these agents, the clinical efficacy of buparlisib (BKM120), a pan-PI3K inhibitor, has been demonstrated in breast cancer patients in a phase 3 trial, and the presence of a PIK3CA mutation was shown to predict a response to this agent." (PMID 28068934, 2017). "Approximately 25% of breast cancer tumours have mutations in the gene encoding the kinase active p110α subunit of PI3K (PIK3CA), with the majority of mutations located in the kinase domain." (PMID 28060760, 2017). "This held true when only breast cancer cells harboring PIK3CA-activating mutations, which are known to be sensitive to PI3Kα inhibition, were considered in the analysis." (PMID 27451907, 2016). "The pooled SE and SP of PIK3CA mutation detection in cfDNA of breast cancer was 0.86 (95% confidence interval [CI] 0.32–0.99) and 0.98 (95% CI 0.86–1.00), respectively; the pooled PLR, NLR were 42.8 (95% CI 5.1–356.9) and 0.14 (95% CI 0.02–1.34), respectively." (PMID 27336598, 2016). "Taken together, our data highlight the activation of IGF1R/p110β/AKT/mTOR as a mechanism of resistance to BYL719 in PIK3CA-mutated breast cancer cells." (PMID 27048245, 2016). "Based on detection in some breast cancer precursors, PIK3CA mutations have been proposed to have a role in tumor initiation." (PMID 27797363, 2016). "It is important to note that we observed the strongest FOXO-dependent effect of LOM612 in the MCF7 breast cancer cell line, which contains an oncogenic missense mutation in PIK3CA." (PMID 27936162, 2016). "This meta-analysis proved that detecting PIK3CA gene mutation by cfDNA has high diagnostic accuracy in breast cancer, especially for metastatic breast cancer." (PMID 27336598, 2016). "In conclusion, our meta-analysis supports the notion that detecting PIK3CA gene mutation in cfDNA has high diagnostic value in breast cancer patients, especially for MBC." (PMID 27336598, 2016). "Two cases with PIK3CA mutation were observed in which 1 patient had best response of PR (breast cancer, PIK3CA mutation at N345K, treatment duration 51 weeks) and another patient had SD (ovarian cancer, PIK3CA mutation at H1047R, treatment duration 16 weeks)." (PMID 26686201, 2016).
breast cancer (continued). "In breast cancer, PIK3CA is mutated in up to 25% of patients, with mutation frequencies rising to 40% in the hormone receptor-positive subgroups." (PMID 26980749, 2016). "Point mutations in PIK3CA are seen frequently in tumors and approximately 40% of breast cancer PIK3CA mutations are due to a single amino acid substitution allele, PIK3CAH1047R, which causes elevated kinase activity." (PMID 26809587, 2016). "In patients with advanced breast cancer (cohort B), 100 % concordance, as well as a 100 % mutation capture rate for ctDNA versus tissue DNA, was observed for PIK3CA by BEAMing." (PMID 27515171, 2016). "Subunit p110 alpha of phosphatidylinositol 3-kinase (PIK3CA) is one of the most commonly mutated oncogenes in breast cancer, which presents in more than 20% of HER2-positive tumors." (PMID 27336598, 2016). "Up to 44 % of all breast cancer subtypes bear PI3K pathway aberrations such as PIK3CA, PIK3R1, AKT1, and PTEN mutations, in particular luminal A (53.4 %) and ERBB2-enriched (47 %) subtypes, although much less common in the basal-like (10 %) subtype." (PMID 27590516, 2016). "Mutational screening of PIK3CA was performed in 102 primary breast cancers and one lymph-node metastasis." (PMID 27765917, 2016). "To investigate the consistency of DRS with these observations, we first stratified TCGA breast cancer patient samples on PIK3CA mutation status and compared their DRSLY-294002." (PMID 27589846, 2016). "Amplification and/or mutation of PIK3CA, the gene encoding the p110α catalytic subunit, occurs in 20–40 % of breast cancers, leading to an increase in activity of the enzyme." (PMID 27048245, 2016). "Due to the predictive and prognostic value of PIK3CA mutation in HER2-positive breast cancer, PIK3CA genotyping is of great importance for tailoring precise and personalized treatment." (PMID 27336598, 2016). "Both cell lines harbor the H1047R substitution mutation, which is one of the most commonly reported activating mutations for PIK3CA in breast cancer." (PMID 27153554, 2016). "Mutations in PIK3CA, a gene encoding the catalytic p110a subunit, were found in 30% of breast cancer." (PMID 27564098, 2016). "We conclude that p110β inhibition circumvents the resistance of PIK3CA-mutated breast cancer cells to BYL719." (PMID 27048245, 2016). "Amplification of mutant PIK3CA alleles appears to contribute to resistance to PI3K inhibitors in preclinical breast cancer models." (PMID 27576528, 2016). "Previous studies in NSCLC and breast cancer cells have shown that the PIK3CA-E545K mutation results in constitutive activation of the PI3K pathway and enhanced signaling through the Akt pathway." (PMID 27489350, 2016). "Recently, knock-in of the mutation into a luminal breast cancer cell-line model against a PIK3CA wild-type background was shown to restore pathway signaling, proliferation, and tumor growth in vivo." (PMID 27515171, 2016). "Among the known breast cancer driver genes, PIK3CA is the most frequently mutated gene associated with a low histologic grade in IDC." (PMID 27811364, 2016). "We find mutually exclusive associations between EECTGs and somatic mutations in mutated genes, such as PIK3CA in breast cancer." (PMID 26813108, 2016). "Results obtained from The Cancer Genome Atlas Network for both colorectal and breast cancer showed the co-existence of mutations in these genes, although in low proportions (4.93% for PIK3CA and KIT and 1.23% for KIT and RET)." (PMID 26968814, 2016). "We have previously reported in a series of Swedish stage II sporadic breast carcinomas that mutations of PIK3CA and loss of PTEN are mutually exclusive." (PMID 27484095, 2016).